UQCRC2 (ubiquinol-cytochrome c reductase core protein 2)
Description:
Component of the ubiquinol-cytochrome c oxidoreductase, a multisubunit transmembrane complex that is part of the mitochondrial electron transport chain which drives oxidative phosphorylation. The respiratory chain contains 3 multisubunit complexes succinate dehydrogenase (complex II, CII), ubiquinol-cytochrome c oxidoreductase (cytochrome b-c1 complex, complex III, CIII) and cytochrome c oxidase (complex IV, CIV), that cooperate to transfer electrons derived from NADH and succinate to molecular oxygen, creating an electrochemical gradient over the inner membrane that drives transmembrane transport and the ATP synthase. The cytochrome b-c1 complex catalyzes electron transfer from ubiquinol to cytochrome c, linking this redox reaction to translocation of protons across the mitochondrial inner membrane, with protons being carried across the membrane as hydrogens on the quinol. In the process called Q cycle, 2 protons are consumed from the matrix, 4 protons are released into the intermembrane space and 2 electrons are passed to cytochrome c (By similarity). The 2 core subunits UQCRC1/QCR1 and UQCRC2/QCR2 are homologous to the 2 mitochondrial-processing peptidase (MPP) subunits beta-MPP and alpha-MPP respectively, and they seem to have preserved their MPP processing properties (By similarity). May be involved in the in situ processing of UQCRFS1 into the mature Rieske protein and its mitochondrial targeting sequence (MTS)/subunit 9 when incorporated into complex III (Probable).
Synonyms: QCR2; UQCR2; MC3DN5
Tractability: Small molecule: a structure with a bound ligand is known. Antibody: UniProt places it where antibodies can reach, with medium confidence. PROTAC: ubiquitination databases record sites on it; its protein half-life has been measured.
Gene: Protein-coding gene on chromosome 16 (21,952,636 to 21,985,391, forward strand). Ensembl gene ENSG00000140740.
Subcellular location: Mitochondrion inner membrane
Subcellular location (Human Protein Atlas): Mitochondria
Pathways (Reactome):
Metabolism: Complex III assembly; Respiratory electron transport
Metabolism of proteins: Mitochondrial protein degradation
Gene Ontology:
Molecular function: protein binding; metal ion binding; metalloendopeptidase activity
Biological process: aerobic respiration; cellular respiration; mitochondrial electron transport, ubiquinol to cytochrome c; oxidative phosphorylation; proteolysis
Cellular component: mitochondrial inner membrane; mitochondrion; respiratory chain complex III
Genetic constraint (gnomAD): Loss-of-function variants: 48 observed, 54.62 expected, observed/expected ratio (o/e) 0.88, 90% interval 0.7 to 1.12. The upper end of that interval is the gene's LOEUF score, 1.12, which puts it in group 4 of 6, group 1 being the genes least tolerant of losing a copy. Missense variants: 498 observed, 568.7 expected, observed/expected ratio (o/e) 0.88, 90% interval 0.81 to 0.94. Synonymous variants: 191 observed, 200.28 expected, observed/expected ratio (o/e) 0.95, 90% interval 0.85 to 1.08.
Gene-disease validity (ClinGen):
ClinGen rates the evidence that UQCRC2 causes each of these diseases.
mitochondrial disease (autosomal recessive): Moderate.
Homologues: Orthologues: chimpanzee UQCRC2 (99% identical), macaque UQCRC2 (97% identical), guinea pig UQCRC2 (91% identical), pig UQCRC2 (88% identical), mouse Uqcrc2 (85% identical), dog UQCRC2 (84% identical), rat Uqcrc2 (83% identical), tropical clawed frog uqcrc2 (70% identical), zebrafish uqcrc2b (60% identical), Caenorhabditis elegans ucr-2.2 (25% identical). Paralogues in human: PMPCA (27% identical), PMPCB (26% identical), UQCRC1 (21% identical), NRDC (21% identical), PITRM1 (20% identical), IDE (18% identical).
Diseases named in the same sentence as UQCRC2 in open-access papers:
UQCRC2 is named in the same sentence as 77 diseases in open-access papers, as found by Europe PMC text mining. Sharing a sentence is not in itself a finding about the gene and the disease. The quoted sentences say what the papers report.
breast carcinoma (7 papers, 2010 to 2023). "Abnormal UQCRC2 expression is associated with the invasion and metastasis of several cancers, such as colorectal cancer 5, breast cancer 6 and testicular cancer." (PMID 32742452, 2020). "Substantially lower content of UQCRC2 has also been reported in breast cancer cells compared to normal cells." (PMID 37482618, 2023). "Multiple studies have shown that UQCRC2 plays a crucial role in the progression and metastasis of numerous cancers, including colorectal cancer, breast cancer, testicular cancer, among others." (PMID 34565283, 2021). "Meanwhile, UQCRC2 levels are reported to be altered in many cancers, including testicular cancer and breast cancer 15-17." (PMID 32742452, 2020). "Similarly, UQCRC2 levels are altered in cancer cells, showing a decrease in mitochondria from breast cancer cells as compared to normal breast cells." (PMID 21049007, 2010). "Ubiquinol-cytochrome C reductase core protein II (UQCRC2), a subunit of complex III, is also elevated in breast cancers." (PMID 37046596, 2023).
colorectal cancer (7 papers, 2020 to 2025). A primary or metastatic malignant neoplasm that affects the colon or rectum. "Next, we examined the expressions of genes encoding mitochondrial components (SDHB, UQCRC2) and LDs in tumor tissues of colorectal cancer patients or in tumor grafts." (PMID 39856069, 2025). "UQCRC2 is a mitochondrial respiratory complex III subunit that is up-regulated in colorectal cancer and can accelerate its proliferation and metastasis." (PMID 32742452, 2020). "Furthermore, NDUFB8, UQCRC2, COX4I1, and ATP5A low levels were associated with lower relapse-free survival in colorectal cancer patients." (PMID 39595536, 2024).
glioma (6 papers, 2020 to 2025). A benign or malignant brain and spinal cord tumor that arises from glial cells (astrocytes, oligodendrocytes, ependymal cells). "The iTRAQ-based quantitative analysis showed that CDH18 was downregulated in tumor tissue from patients with glioma, and its downstream target, UQCRC2, was down-regulated in tumor tissue from patients with glioma compared to healthy tissue." (PMID 34631760, 2021). "On the other hand, UQCRC2 can inhibit glioma progression as it mediates the effect of cadherin 18 on suppressing the invasion of glioma cells." (PMID 34361072, 2021). "For example, CDH18 was shown to inhibit invasion/migratory ability and chemoresistance via ubiquinol cytochrome c reductase core protein 2 (UQCRC2) in gliomas,and reduce malignancy in gastric cancer via the constitutive photomorphogenesis 1 (COP1)-PI3K/AKT pathway axis." (PMID 40017628, 2025).
gastric cancer (5 papers, 2020 to 2025). A primary or metastatic malignant neoplasm involving the stomach. "This study investigated the role of UQCRC2 in gastric cancer (GC) and its upstream regulatory microRNAs (miRNAs)." (PMID 32742452, 2020).
testicular cancer (5 papers, 2020 to 2022). A primary or metastatic malignant neoplasm that affects the testis. "Uqcrc2 is a component of the biquinol‐cytochrome reductase complex, which is associated with spermatogenesis, and has been shown to be a biomarker for clinical varicocele and asthenozoospermic testicular cancer patients associated infertility." (PMID 34894202, 2022).
Alzheimer disease (4 papers, 2016 to 2025). A progressive, neurodegenerative disease characterized by loss of function and death of nerve cells in several areas of the brain leading to loss of cognitive function such as memory and language. "In additionto cardiomyopathy- and metabolic-related pathways, we noted thatTmem43-associated mitochondrial genes, NDUFS6and UQCRC2, are enriched in neurodegenerative disease-relatedpathways, including Alzheimer’s disease (AD), Parkinson’s disease(PD), and Huntington’s disease (HD)." (PMID 34766515, 2022).
Hypoglycemia (4 papers, 2017 to 2023). A decreased concentration of glucose in the blood. "Several pathogenic UQCRC2 variants have been identified in patients presenting with metabolic abnormalities that include lactic acidosis, hyperammonemia, hypoglycemia, and organic aciduria." (PMID 37709555, 2023). "These individuals with mutations in UQCRB, UQCRC2, and CYC1 presented with neonatal or early infancy onset, recurrent metabolic crises with elevated lactate and hypoglycaemia, from which they completely and quickly recovered with intravenous glucose." (PMID 28804536, 2017). "She experienced recurrent episodes of metabolic decompensation, including hypoglycemia and lactic acidosis, and was found by whole-exome sequencing (WES) to be heterozygous for two novel missense variants in UQCRC2 (c.1189G>A; p.Gly397Arg and c.437T>C; p.Phe146Ser)." (PMID 37709555, 2023). "The UQCRC2 (ubiQuinol‐cytochrome c reductase core protein II) gene encodes a subunit of mitochondrial complex III; the homozygous mutations of the gene can give neonatal acidosis with hyperammonemia and hypoglycemia." (PMID 37405046, 2023). "Disruptions in UQCRC2 have been associated with mitochondrial complex III deficiency nuclear type 5, which results in a variety of disorders including mitochondrial encephalopathy, liver dysfunction, renal tubulopathy, hypoglycemia, and exercise intolerance." (PMID 34884479, 2021). "Thus in addition to anomalies frequently observed in oxidative phosphorylation defects, patients with UQCRC2 defects could also have some abnormalities that are less characteristic, including hypoglycemia and hyperammonemia." (PMID 37709555, 2023).
prostate carcinoma (3 papers, 2018 to 2024). A carcinoma that arises from epithelial cells of the prostate gland. "mRNA expression of key mitochondrial genes, including NDUFB8, UQCRC2, and COXI, was decreased with POLRMT silencing or inhibition, but increased with POLRMT overexpression in prostate cancer cells." (PMID 37816734, 2023). "Importantly, in POLRMT-silenced prostate cancer xenograft tissues, NDUFB8, UQCRC2, and COXI downregulation as well as oxidative stress, lipid peroxidation, and ATP reduction were detected as well." (PMID 37816734, 2023).
sleep disorder (3 papers, 2022 to 2025). A change from the patient's baseline sleeping pattern, in the hours slept and/or an alteration/dysfunction in the stages of sleep. "ATP5B, COX5A, GAPDH NDUFV2, SOD1, UQCRC1, and UQCRC2 have been reported as sleep deprivation and sleep disorder-related genes, and these studies have contributed to the development of candidate biomarkers for the diagnosis and treatment of plateau-induced sleep disorders." (PMID 36860517, 2023).
hepatocellular carcinoma (2 papers, 2020 to 2021). A malignant tumor that arises from hepatocytes. "There are examples of UQCRH levels correlating with other CIII subunits, such as UQCRB, UQCRC2 and CYC1 expression in hepatocellular carcinoma." (PMID 34750991, 2021).
Hyperammonemia (2 papers, 2023). An increased concentration of ammonia in the blood. "This case highlights two novel, likely pathogenic variants in UQCRC2 identified in a 3-yr-old patient presenting with lactic acidosis, hyperammonemia, and lethargy." (PMID 37709555, 2023).
ischemia (2 papers, 2010 to 2021). A hypoperfusion of the BLOOD through an organ or tissue caused by a PATHOLOGIC CONSTRICTION or obstruction of its BLOOD VESSELS, or an absence of BLOOD CIRCULATION. "The GTT-offered protection of ischemia-induced decreases in complex III activity was accompanied by elevated mitochondrial levels of core protein 2 (UQCRC2) and the Rieske Fe-S protein subunit of complex III." (PMID 34884479, 2021).
lactic acidosis (2 papers, 2021 to 2023). Metabolic acidosis characterized by the accumulation of lactate in the body. "Furthermore, pathogenic variants identified in cytochrome b‐c1 complex subunit 2 (UQCRC2) have been associated with episodic severe metabolic acidosis and hyperammonaemia, hypoglycaemia and lactic acidosis in four patients." (PMID 34750991, 2021). "Some present very similarly to the cases we describe, for example, patients with UQCRC2 variants showed episodes of metabolic decompensation with lactic acidosis, hypoglycaemia, ketosis and hyperammonaemia without neurological impairment." (PMID 34750991, 2021).
melanoma (2 papers, 2012 to 2017). A malignant, usually aggressive tumor composed of atypical, neoplastic melanocytes. "In A375 human melanoma cells (which do not appear to express p16 constitutively), forced expression of p16 resulted in marked downregulation of ND4, SDHA and UQCRC2, while the reduction in PRC and TFAM was less striking." (PMID 28915557, 2017).
non-alcoholic fatty liver disease (2 papers, 2023 to 2024). "Six of the key metagenes—INSR, MAP3K5, NDUFB8, NDUFS1, SDHB, and UQCRC2—are involved in nonalcoholic fatty liver disease (hsa04932), which is caused by a defect in insulin suppression of free fatty acid (FAA) disposal due to the induction of insulin resistance." (PMID 36979367, 2023).
varicocele (2 papers, 2020 to 2022). A condition characterized by the dilated tortuous veins of the spermatic cord with a marked left-sided predominance. "UQCRC2 is reportedly involved in the TCA cycle and its underexpression has been correlated with poor fertilization rates and male infertility conditions, such as varicocele." (PMID 32942548, 2020).
cognitive decline (1 paper, 2022). "Thus, the omics data reveal that the reduced FBP1 and ALDOB and increased UQCRC2 can contribute to cognitive decline in T2DM patients through the mechanisms involving deregulated glucose metabolism and acidosis." (PMID 36506101, 2022). "The bioinformatics data together indicate that upregulation of SERPINA1, VCP, PRNP, CIP2A, HSPA9, and UQCRC2 and downregulation of IGFBP3, CRHBP, PEPD, and GUSB were correlated to cognitive decline in T2DM patients." (PMID 36506101, 2022).
developmental delays (1 paper, 2023). "Almost all previously reported UQCRC2-deficient patients exhibited neurodevelopmental involvement, including developmental delays and structural brain anomalies." (PMID 37709555, 2023).
emphysema (1 paper, 2022). "ND1 expression was significantly increased and UQCRC2 levels were decreased in emphysema patients compared to smokers." (PMID 35884802, 2022). "Decreases in ND1 and UQCRC2 expression levels were found in ATII cells in emphysema." (PMID 35884802, 2022). "ND1, UQCRC2, and COX4 levels were decreased in ATII cells in emphysema compared to smokers by Western blotting." (PMID 35884802, 2022). "UQCRC2 mRNA expression was significantly higher in emphysema in comparison with nonsmokers." (PMID 35884802, 2022).
encephalomyopathy (1 paper, 2024). "On the other hand, the consistent finding of extensively interconnected mitochondrial networks observed in UQCRC1-mutant cells is also found in UQCRC2-mutant fibroblasts derived from patients with severe encephalomyopathy." (PMID 38666843, 2024).
epilepsy (1 paper, 2025). A brain disorder characterized by episodes of abnormally increased neuronal discharge resulting in transient episodes of sensory or motor neurological dysfunction, or psychic dysfunction. "UQCRC2 (cytochrome b-c1 complex subunit 2) is the only Mendelian disease gene in this region in which mutations may cause epilepsy." (PMID 40861674, 2025). "Epilepsy may also occur in patients with UQCRC2 mutations; however, this does not adequately account for the PKD phenotype." (PMID 40861674, 2025).
liver fibrosis (1 paper, 2024). "ART also reduced liver fibrosis caused by schistosomiasis through the downregulation of NDUFB8, a subunit of mitochondrial complex I, and UQCRC2, a subunit of mitochondrial complex III in hepatic stellate cells." (PMID 39476067, 2024).
lung carcinoma (1 paper, 2024). "Expression levels of MTCO1, UQCRC2, and COXIV were higher in BrM lesions as compared with primary lung cancers." (PMID 39593114, 2024). "Moreover, we performed the IHC staining of 49 pairs of primary lung cancers and BrM lesions from both SYSUCC and WCH cohorts in order to independently validate the expression of MTCO1, UQCRC2, and COXIV at the protein level." (PMID 39593114, 2024).
lymph node metastasis (1 paper, 2020). "Furthermore, UQCRC2 levels were negatively correlated with lymph node metastasis, relapse, and tumor grade." (PMID 32742452, 2020).
male fertility (1 paper, 2013). A fertility quality of inhering in a male by virtue of the bearer's disposition to initiate, sustain, or support reproduction. "Notably, the decreased UQCRC2 and TYP were associated with reduced sperm kinematics, ATP production, and capacitation, which ultimately led to adverse effects on male fertility such as poor fertilization rates and embryo development." (PMID 24130818, 2013).
myocarditis (1 paper, 2019). Myocarditis is a condition that is characterized by inflammation of the heart muscle (myocardium). "Cytochrome c reductase complex III, including UQCRQ, UQCRC1, UQCRC2, are oxidatively damaged in response to infection in chagasic myocarditis hearts." (PMID 31275164, 2019).
Obesity (1 paper, 2017). Accumulation of substantial excess body fat. "UQCRC2 was shown to be downregulated in individuals who were susceptible to weight gain and obesity development." (PMID 28396702, 2017).
selenium deficiency (1 paper, 2021). A nutritional deficiency disease resulting from inadequate selenium levels in the body, which can lead to impaired function of selenoproteins essential for antioxidant defense and thyroid hormone metabolism. "Complex III (ubiquinol‐cytochrome C reductase core protein 2, UQCRC2) and complex V (ATP synthase F1 subunit alpha, ATP5A) protein abundance were not affected by maternal selenium deficiency in either sex." (PMID 33769708, 2021).
Trypanosoma cruzi infection (1 paper, 2025). "Complex 3 (CoQ: cytochrome c-oxidoreductase) deficiency is responsible for fewer mitochondrial disorders, although carbonylation of genes like Uqcrc2 (found as downregulated in both untreated CCC and IHF) is a direct response to the stress of Trypanosoma cruzi infection." (PMID 41296444, 2025).